SBSPON (somatomedin B and thrombospondin type 1 domain containing)
Synonyms: C8orf84; RPESP
Tractability: Antibody: UniProt places it where antibodies can reach, with high confidence; UniProt predicts a signal peptide or a membrane-spanning region; its Gene Ontology location is reachable by antibodies, with medium confidence.
Gene: Protein-coding gene on chromosome 8 (73,064,543 to 73,124,088, reverse strand). Ensembl gene ENSG00000164764.
Subcellular location: Secreted, extracellular space, extracellular matrix
Subcellular location (Human Protein Atlas): Vesicles; Predicted to be secreted
Pathways (Reactome):
Disease: Defective B3GALTL causes PpS
Metabolism of proteins: O-glycosylation of TSR domain-containing proteins
Gene Ontology:
Molecular function: extracellular matrix structural constituent
Cellular component: extracellular matrix; non-collagenous component of interstitial matrix
Genetic constraint (gnomAD): Loss-of-function variants: 15 observed, 19.44 expected, observed/expected ratio (o/e) 0.77, 90% interval 0.51 to 1.19. The upper end of that interval is the gene's LOEUF score, 1.19, which puts it in group 5 of 6, group 1 being the genes least tolerant of losing a copy. Missense variants: 239 observed, 227.51 expected, observed/expected ratio (o/e) 1.05, 90% interval 0.94 to 1.17. Synonymous variants: 97 observed, 95.58 expected, observed/expected ratio (o/e) 1.01, 90% interval 0.86 to 1.2.
Homologues: Orthologues: chimpanzee SBSPON (98% identical), macaque SBSPON (98% identical), rabbit SBSPON (93% identical), pig SBSPON (90% identical), dog SBSPON (90% identical), mouse Sbspon (89% identical), rat Sbspon (89% identical), guinea pig SBSPON (88% identical), tropical clawed frog sbspon (63% identical), zebrafish SBSPON (55% identical), Caenorhabditis elegans sbsp-1 (32% identical), Drosophila melanogaster vex (30% identical).
Diseases named in the same sentence as SBSPON in open-access papers:
SBSPON is named in the same sentence as 11 diseases in open-access papers, as found by Europe PMC text mining. Sharing a sentence is not in itself a finding about the gene and the disease. The quoted sentences say what the papers report.
bladder cancer (1 paper, 2025). "In our investigation, we have substantiated low expression of SBSPON in bladder cancer through comprehensive data mining and two independent internal cohort studies, yielding robust and dependable outcomes." (PMID 40765821, 2025). "Consistently, in TCGA database, SBSPON was significantly downregulated in various types of tumors as compared with normal tissues, including bladder cancer." (PMID 40765821, 2025). "Among these mutations, only the mutation at Asn227 resulted in a lower molecular weight compared to the wild-type SBSPON protein in bladder cancer, suggesting that the potential of glycosylation modification at the Asn227 site." (PMID 40765821, 2025). "The results showed that SBSPON overexpression induced an epithelial phenotype by reducing mesenchymal markers (Vimentin, N-cadherin and Snail) while increasing the epithelial marker E-cadherin, suggesting that SBSPON inhibits EMT in bladder cancer cells." (PMID 40765821, 2025). "In summary, the novel glycoprotein SBSPON functions as a tumor suppressor and inhibits resistance to cisplatin in bladder cancer." (PMID 40765821, 2025). "Conversely, the number of bladder cancer cells in the G0/G1 phase and the apoptotic rates were significantly decreased when SBSPON was silenced in SW780 and UMUC3." (PMID 40765821, 2025). "The overexpression SBSPON significantly decreased the IC50 of DDP in bladder cancer cells compared with the control, while slightly reduced the IC50 of TM." (PMID 40765821, 2025). "The expression of SBSPON was downregulated in bladder cancer and correlated with poor overall survival." (PMID 40765821, 2025). "We found that SBSPON downregulation in bladder cancer is closely associated with tumor clinical staging, pathological grade, regional lymph node metastases, and bladder cancer patients with low SBSPON expression have a worse prognosis survival prognosis." (PMID 40765821, 2025). "Taken together, these results provide strong evidence that SBSPON inhibits the tumorigenesis of bladder cancer." (PMID 40765821, 2025). "Our findings highlight the potential of SBSPON as a potential biomarker and therapeutic target, and provide new insights into tumor progression and resistance to cisplatin in bladder cancer." (PMID 40765821, 2025). "Cox regression analysis was performed to identify whether the expression of SBSPON is an independent prognostic factor of bladder cancer." (PMID 40765821, 2025). "In the present study, we identified SBSPON as a tumor suppressor in bladder cancer." (PMID 40765821, 2025). "Collectively, our study indicated that SBSPON has the potential to serve as a biomarker for bladder cancer, and this may provide novel therapeutic targets for bladder cancer treatment." (PMID 40765821, 2025). "In addition, SBSPON knockdown significantly increase tumor volume in an in vivo xenograft model of bladder cancer." (PMID 40765821, 2025). "However, the expression of SBSPON was markedly lower in bladder cancer cells, and significantly decreased in bladder tumor tissues as compared with adjacent normal tissues." (PMID 40765821, 2025). "In conclusion, SBSPON was identified as a novel-tumor suppressor molecule for bladder cancer." (PMID 40765821, 2025). "Therefore, we analyzed the effects of SBSPON overexpression on several csHSPA5-related pathways in bladder cancer cells." (PMID 40765821, 2025). "We revealed that SBSPON regulates the expression of EMT-related markers, such as E-cadherin, N-cadherin, Vimentin and Snail, leading to reduced migration and invasion of bladder cancer cells." (PMID 40765821, 2025). "In the present study, we identified SBSPON as a novel HSPA5 binding glycoprotein and tumor suppressor, and investigated the molecular mechanism of its cellular function and regulatory roles in bladder cancer progression and cisplatin resistance." (PMID 40765821, 2025).
bladder cancer (continued). "The overexpression of SBSPON can significantly counteract the growth promotion and the inhibition of apoptosis of HSPA5 overexpression on bladder cancer cells when treated with DDP and TM, while the overexpression of HSPA5 had the opposite effects on bladder cancer cells with overexpressed SBSPON." (PMID 40765821, 2025). "Overall, this study highlighted the significant finding that SBSPON could modulate ER stress signaling by interacting with HSPA5 and further enhanced apoptosis following chemotherapy in bladder cancer by promoting ER stress-induced cell death." (PMID 40765821, 2025). "Moreover, SBSPON could modulate ER stress signaling through competitively binding HSPA5 with ER sensors PERK under ER stress and further potentiate apoptosis during chemotherapy treatment for bladder cancer through the induction of ER stress." (PMID 40765821, 2025).
bladder tumors (1 paper, 2025). "The results showed that SBSPON protein was mainly visible in normal bladder urothelial cells as intermediate to intense cytoplasmic staining, and significantly decreased in bladder tumor cells." (PMID 40765821, 2025).
cervical adenocarcinoma (1 paper, 2020). An adenocarcinoma arising from the cervical epithelium. "MiRNA-mRNA interactions by miranda and targetscan analysis showed that the downregulated expression of CADM1, SBSPON, and FAM229B in cervical adenocarcinoma samples might be the potential target genes for miR-192-5p." (PMID 33024199, 2020).
cystinuria (1 paper, 2017). Cystinuria is a renal tubular amino acid transport disorder characterized by recurrent formation of kidneys cystine stones. "Up-regulated genes included several genes (SLC7A9, SEMG1, SBSPON and MEGF6) that were not well functionally characterized (except SLC7A9, a marker for cystinuria) and are not discussed here." (PMID 29284484, 2017).
gastric cancer (1 paper, 2022). A primary or metastatic malignant neoplasm involving the stomach. "GSEA indicates that the low expression of SBSPON in gastric cancer tissues is related to aminoacyl-tRNA biosynthesis, citrate cycle, fructose and mannose metabolism, pentose phosphate pathway and pyrimidine metabolism." (PMID 36419649, 2022). "We further analyzed the mRNA level expression of SBSPON in TCGA and found that it was lowly expressed in gastric cancer tissues." (PMID 36419649, 2022).
lymph node metastasis (1 paper, 2025). "Multivariate cox regression analysis demonstrated that the regional lymph node metastasis and the relative level of SBSPON expression was an independent prognostic factor for poor overall survival (P = 0.015 and P = 0.026, respectively)." (PMID 40765821, 2025).
tumor (4 papers, 2023 to 2025). "To provide more convincing evidence unraveling that SBSPON is involved with drug resistance of tumor cells through binding to HSPA5 under ER stress, we performed Co-Immunoprecipitation between HSPA5 and PERK." (PMID 40765821, 2025). "In the present study, we identify SBSPON (Somatomedin B and Thrombospondin Type 1 Domain Containing) as a novel tumor suppressor." (PMID 40765821, 2025). "The results showed that SBSPON was widely expressed in most normal human tissues while its expression was variable in different human tumor cell lines." (PMID 40765821, 2025). "The results showed that overexpression of SBSPON suppressed tumor growth." (PMID 40765821, 2025). "We investigated whether SBSPON was involved with drug resistance of tumor cells under ER stress." (PMID 40765821, 2025). "The genes expression levels in the model were detected by qRT-PCR, and the results showed that they were highly expressed in 20 pairs of tumor and normal tissues (UNCX, SLC6A3, AGAP2-AS1, LINC00968, PTX3 and SBSPON), while ITPRID1, DCST2, ETV3L, and ENSG00000261327 were down-regulated." (PMID 36647156, 2023).
cancer (2 papers, 2023 to 2025). A tumor composed of atypical neoplastic, often pleomorphic cells that invade other tissues. "SBSPON, one of the cancer associated genes, is part of the extracellular matrix and is associated with O-glycosylation (OGT) of proteins, which is linked to nutrient availability and overexpression of OGT can lead to a decrease in lipolysis in adipose tissue." (PMID 37456561, 2023). "Our data revealed that the overexpression of SBSPON can slightly increase the amount of HSPA5 protein, which seems to contradict the anti-cancer function of SBSPON." (PMID 40765821, 2025).
adenocarcinoma (1 paper, 2020). A common cancer characterized by the presence of malignant glandular cells. "The potential predicted targets of miR-192-5p include CADM1, SBSPON and FAM229B, which were down-regulated in adenocarcinoma from our transcriptome sequencing data." (PMID 33024199, 2020).
SBSPON also shares sentences with these, for which no sentence is quoted: colon cancer (1 paper); metastatic disease (1).